IKZF1 (IKAROS family zinc finger 1)
Diseases named in the same sentence as IKZF1 in open-access papers (continued):
Sharing a sentence is not in itself a finding about the gene and the disease.
peritonitis (1 paper, 2025). Inflammation of the peritoneum (tissue that lines the abdominal wall and covers most of the organs in the abdomen). "This study establishes IKZF1 as a potential biomarker and therapeutic target for mitigating excessive inflammation in peritonitis." (PMID 41019036, 2025). "This study aimed to investigate the molecular mechanism of IKZF1 in regulating inflammatory responses during acute peritonitis." (PMID 41019036, 2025). "Using a murine CLP-induced peritonitis model, we analyzed IKZF1 expression in macrophages via RT-qPCR and western blot." (PMID 41019036, 2025). "IKZF1 exacerbates macrophage inflammation in CLP-induced peritonitis by epigenetically silencing SDHB via HDAC3-mediated deacetylation, thereby disrupting mitochondrial metabolism and amplifying pro-inflammatory signals." (PMID 41019036, 2025). "To ascertain the potential role of Len in mitigating acute peritonitis by inhibiting IKZF1, we conducted a series of experiments." (PMID 41019036, 2025). "In this study, we demonstrated that IKZF1 intensifies inflammatory reactions through the epigenetic regulation of macrophage mitochondria dysfunction in acute peritonitis." (PMID 41019036, 2025). "We are further evaluating the impact of IKZF1 inhibition on lung injury triggered by acute peritonitis." (PMID 41019036, 2025). "The epigenetic changes mediated by IKZF1 can lead to a sustained pro-inflammatory phenotype in macrophages, thereby exacerbating the immune response following acute peritonitis." (PMID 41019036, 2025). "We found that IKZF1 inhibition significantly promotes the degradation of HIF-1α without affecting its transcriptional level, further confirming that IKZF1 exacerbates CLP-induced peritonitis by promoting succinate accumulation." (PMID 41019036, 2025). "To validate these findings, we established a CLP-induced acute peritonitis model demonstrating significant elevation of Ikzf1 transcript levels in peritoneal macrophages compared to controls." (PMID 41019036, 2025). "Here we reveal an important regulatory role for IKZF1 in the progression of acute peritonitis." (PMID 41019036, 2025). "Given the inflammatory nature of peritonitis, the regulatory function of IKZF1 in the immune response may make it a potential factor in the pathogenesis of peritonitis." (PMID 41019036, 2025). "Collectively, these findings indicate that the suppression of Ikzf1 expression leads to a notable amelioration of the inflammatory response in acute peritonitis, suggesting that IKZF1 could serve as a promising therapeutic target for the condition." (PMID 41019036, 2025). "Addressing these limitations in future studies could refine the mechanistic understanding of IKZF1 in inflammation and improve the translational relevance of targeting this pathway in peritonitis." (PMID 41019036, 2025). "IKZF1 expression was significantly upregulated in macrophages during CLP-induced peritonitis." (PMID 41019036, 2025). "Therefore, IKZF1 is expected to be an efficient pharmaceutical ingredient, providing new strategies for treating peritonitis." (PMID 41019036, 2025). "Therefore, the alteration of IKZF1 in peritonitis and its potential therapeutic role deserve further exploration." (PMID 41019036, 2025). "Collectively, these findings suggest that the elevated IKZF1 expression in peritoneal macrophages may play a pivotal role in the pathogenesis of acute peritonitis." (PMID 41019036, 2025). "Understanding how IKZF1 influences macrophage behavior in such inflammatory settings may provide insights into potential therapeutic strategies for modulating macrophage function in peritonitis and other inflammatory disorders." (PMID 41019036, 2025). "Overall, IKZF1 collaborates with HDAC3 to inhibit Sdhb expression, which in turn exacerbates macrophage inflammatory responses triggered by peritonitis." (PMID 41019036, 2025).
peritonitis (continued). "In this study, we discovered that IKZF1 collaborates with HDAC3 to regulate the H3K9ac modification, thereby affecting the functional transition of macrophages and participating in the pathological process of acute peritonitis." (PMID 41019036, 2025).
plasma cell dyscrasias (1 paper, 2018). "DC dysregulation is highly likely to have pathological consequences for immunity in germline IKZF1 mutation but confer additional therapeutic benefit in lenalidomide treatment of plasma cell dyscrasias." (PMID 29588478, 2018).
primary effusion lymphoma (1 paper, 2021). A large B-cell lymphoma located in the body cavities, characterized by pleural, peritoneal, and pericardial fluid lymphomatous effusions and that is always associated with human herpes virus-8 (HHV-8). "Disruption of the IKZF1/3-IRF4-MYC transcriptional axis is of specific importance in MM, as studies have shown that in other diseases, such as primary effusion lymphoma, degradation of IKZF1/3 is uncoupled from lenalidomide-induced suppression of IRF4 and MYC." (PMID 34834536, 2021).
rectal cancer (1 paper, 2022). A primary or metastatic malignant neoplasm that affects the rectum. "This quantitative ctDNA test measuring levels of methylated BCAT1/IKZF1 DNA in blood reflects tumor burden at diagnosis and provides a baseline for demonstrating response to differing therapeutic approaches for colon and rectal cancer." (PMID 35000264, 2022).
sarcoma (1 paper, 2025). A usually aggressive malignant neoplasm of the soft tissue or bone. "Moreover, low IKZF1 expression was identified as a prognostic factor associated with poor outcomes in OS patients (TARGET-OS) and in sarcoma patients (TCGA-SARC)." (PMID 39983717, 2025).
skin infection (1 paper, 2020). An inflammatory process affecting the skin, caused by bacteria, viruses, parasites, or fungi. "The patient carried the IKZF1-p.His191Tyr mutation in heterozygous state (as mentioned in Subjects), and his diagnosis was established when his brother (family proband) was also diagnosed with CVID due to recurrent ATP and a history of recurrent skin infections." (PMID 33274244, 2020).
Stevens-Johnson syndrome (1 paper, 2020). Stevens-Johnson syndrome is a limited form of toxic epidermal necrolysis characterized by destruction and detachment of the skin epithelium and mucous membranes involving less than 10% of the body surface area. "In cold medicine-related Stevens-Johnson syndrome, in addition to the Japanese, Korean and Indian populations, Thai cases with cold-related Stevens-Johnson syndrome and severe ocular complications were significantly associated with IKZF1 single nucleotide polymorphism (SNPs)." (PMID 33292572, 2020).
tumor (120 papers, 2012 to 2026). "Reduced expression of IKZF1 is associated with increased tumour immune evasion and progression in various malignancies, indicating its role as tumour suppressor and prognostic marker." (PMID 40041934, 2025). "As ICB induces differentiation of Tpex cells into Tex cells, we tested the effect of Ikzf1 deficiency on ICB responses by treating tumour-bearing mice that received sgNTC or sgIkzf1 OT-I cells with anti-PD-L1." (PMID 37968405, 2023). "Of note, Ikzf1, Spi1, Tcf3, and Pax5 are normally expressed in induced B cell progenitors, which ensure tumor-free lymphopoiesis as reduction or loss of any of these master factors is associated with B cell leukemia." (PMID 34893754, 2022). "The results revealed that mutations in GNAQ, SEPTIN 6, NTRK3, and IKZF1 occur only in tumor samples." (PMID 35864526, 2022). "Our findings establish a potential regulatory circuit between the tumor-suppressor Ikaros and the oncogenic miRNA networks in IKZF1-mutated B-ALL." (PMID 36278683, 2022). "Here, we found that Ikaros, a tumor suppressor encoded by IKZF1, directly binds to both the BCL6 and BACH2 promoters where it suppresses BCL6 and promotes BACH2 expression in B-cell ALL (B-ALL) cells." (PMID 28030830, 2017). "IMiDs have also been shown to modulate the immune system in addition to causing direct cytotoxicity of tumor cells through the regulation of IKZF1 and IKZF3 protein abundance." (PMID 28264055, 2017). "Normal Ikzf1 expression was associated with increased tumour latency compared to TL with Ikzf1 inactivation." (PMID 26125582, 2015). "Moreover, overexpression of IKZF1 has been associated with increased recruitment of anti-tumor immune cell infiltrates and sensitivity to anti-PD-1 and anti-CTLA4 therapy." (PMID 40428397, 2025). "The lactylation of Ikaros family zinc finger 1 (IKZF1) at lysine 164, for example, enhances the differentiation of Th17 cells by upregulating the expression of Th17-associated genes, including Runx1, Tlr4, IL-2, and IL-4, further contributing to the suppression of anti-tumor immunity." (PMID 39766353, 2024). "If detection of methylated BCAT1/IKZF1 ctDNA is to be useful in patient management, it is important to better understand the principles underlying the presence of these epigenetic markers in blood and how this relates to tissue expression and to tumour debulking." (PMID 29796114, 2018). "Furthermore, the effect size of rs4132601 on ALL risk is ~1.5 to 1.7, hence there are likely to be as yet unidentified functional variants underlying the IKZF1 association signal that may show significant tumor PAI if tested." (PMID 26575185, 2015). "The IKZF1 E–P interaction signal correlated positively with IKZF1 RNA expression as well as leukocyte fraction estimation but negatively with tumor purity estimation." (PMID 40355593, 2025). "The in vivo IHC staining proved that MAT2A inhibition or methionine diet restriction enhanced IKZF1 expression in tumor tissue." (PMID 39983717, 2025). "Pioneering studies have established IKZF1 as a key regulator of lymphocyte development, and an important tumor suppressor in B-ALL (Ref.5–8)." (PMID 39437550, 2025). "In preclinical models, cemsidomide demonstrated sustained IKZF1/3 degradation and durable tumor regressions for a prolonged period after drug discontinuation." (PMID 38473381, 2024). "Actually, Lyn is a target of the Ikaros protein IKZF1, which was shown to increase the immune infiltrate in solid tumors and enhance anti-tumor immunotherapy." (PMID 37834179, 2023). "IKZF1 acts principally as a tumour suppressor via transcriptional repression of oncogenes in normal lymphoid lineages." (PMID 37581569, 2023).
tumor (continued). "One CIS overlaps with Ikzf1 itself and displays the expected gene inactivation-type insertion pattern, consistent with the known tumor-suppressive function of Ikzf1." (PMID 36950387, 2023). "IKZF1 functions as a tumour suppressor via transcriptional repression of oncogenes in normal hematopoietic lineages, whereas it activates IRF4 and other oncogenes in MM cells." (PMID 37581569, 2023). "IKZF1, a well‐known tumour suppressor and transcription factor in haematopoiesis, plays a critical role in lymphoid differentiation, as well as in myeloid development." (PMID 37345307, 2023). "IKZF1 N159S exerted aberrant regulation of cell apoptosis, cell cycle and cell viability, which indicated the perturbation of the tumour‐suppression function of IKZF1." (PMID 37345307, 2023). "IKZF1 encodes IKAROS, which is a critical transcription factor for lymphopoiesis and immune haematopoiesis, and potentially works as a tumour suppressor by negatively regulating cell proliferation." (PMID 37345307, 2023). "This orally bioavailable compound selectively targets IKZF1 (Ikaros) and IKZF3 (Aiolos), causing tumor cell death upon their depletion from malignant B cells and T cell activation when depleted from the tumor microenvironment." (PMID 37669923, 2023). "Most of these genes are reported to be involved in either lymphoid development (such as PAX5 and IKZF1), lymphoid signaling, cell cycle and apoptosis regulation (mostly tumor suppressors such as CDKN2A), DNA repair, therapy response, or transcription factors." (PMID 36980958, 2023). "GSEA analysis indicated that NOTCH signalling, cell cycle, and MYC targets pathways were commonly upregulated in IKZF1 mutants, suggesting the tumour suppressor function of IKZF1." (PMID 37345307, 2023). "Another study showed that IKAROS (IKAROS family zinc finger 1) acts as an essential regulator in KMT2Ar AML by influencing tumor suppressor pathways, immune dysregulation, and changes in cell differentiation." (PMID 37325571, 2023). "A functional relationship was found between LCP1, ITGB2, and IKZF1, suggesting that these genes regulate tumor immunology in COAD by regulating MDSC infiltration." (PMID 36230637, 2022). "This observational study showed a correlation between the levels of methylated BCAT1/IKZF1 ctDNA and tumor burden." (PMID 35000264, 2022). "IKZF2 and IKZF5 were downregulated in the primary tumor, and IKZF1–3 expression decreased significantly as the T-stage or metastasis increased in SKCM." (PMID 36353107, 2022). "IKZF1 is a known tumor-suppressor gene, and high GIMAP6 expression level is also associated with a favorable prognosis in patients with LUAD and LIHC." (PMID 36311703, 2022). "In the current study, we have extended on our previous findings and have shown a close relationship between the amount of circulating methylated BCAT1/IKZF1 DNA and tumor burden at diagnosis." (PMID 35000264, 2022). "So far, three CRL4CRBN substrates have been identified that mediate the anti-tumor activity of IMiDs in hematologic malignancies, including the Ikaros family zinc finger proteins 1 and 3 (IKZF1 and IKZF3) and casein kinase 1 alpha (CK1α)." (PMID 34680233, 2021). "IKAROS, encoded by the IKZF1 gene, is a DNA-binding protein that functions as a tumor suppressor in T cell acute lymphoblastic leukemia (T-ALL)." (PMID 33467550, 2021). "An example of the first strategy is seen in a study that enhances the master regulator IKZF1, leading to an enhanced immune infiltrate recruitment and tumor sensitivity to ICB therapy." (PMID 33291616, 2020). "IKZF1 was described as a tumor suppressor gene based on its role in regulation of cellular proliferation." (PMID 30846004, 2019). "For tumor suppressor genes, IKAROS family zinc finger 1 (IKZF1) is a key regulator factor that enhanced immune infiltrate recruitment and tumor sensitivity in several tumors." (PMID 30867653, 2019).
tumor (continued). "ctDNA methylated in BCAT1 or IKZF1 was detected in 116 (62.0%) cases at diagnosis and was significantly more likely to be detected with later stage (P < 0.001) and distal tumour location (P = 0.004)." (PMID 29796114, 2018). "Pearson’s correlation analysis, which was used to examine the correlation between MDIG and IKZF1 mRNA in HCC tumour tissues, yielded a correlation of -0.397, with a P-value of 0.03." (PMID 28471446, 2017). "Depletion of these transcription factors in MM cell lines leads to inhibition of tumor cell growth, confirming the role of IMiD-mediated degradation of IKZF1 and IKZF3 on reducing myeloma cell proliferation." (PMID 28264055, 2017). "Our previous publications have demonstrated that IKZF1 exerts anti-tumor effects by regulating the expression of its target genes such as c-Myc, PI3KCD, KDM5B, etc.." (PMID 27391346, 2016). "By normalizing to this control locus, we determined genomic copy number estimates of CDKN2A and IKZF1 in tumor DNA samples." (PMID 26575185, 2015). "The biological functions of BCAT1 and IKZF1 are not well understood, but both genes are involved in tumour growth and invasiveness." (PMID 26445409, 2015). "We optimized the BCAT1 and IKZF1 methylation qPCR assays for detection of methylation ratios as low as 0.1%, as such low levels of tumour-derived DNA have been reported in plasma specimens from patients with early stage CRC." (PMID 25928810, 2015). "By modelling the stage of neoplasia relative to marker mass, we show the potential for using the measured percentage of methylated BCAT1 and IKZF1 DNA in blood to estimate the relative risk of disease severity." (PMID 26445409, 2015). "We observed the strong amplification of EGFR and neighboring gene IKZF1 in the primary tumor of patient SK01600, but it seems to be partially lost in the matched neurosphere culture." (PMID 23441165, 2013). "During the last 5 years, IKZF1 has been identified as one of the most clinically relevant tumor suppressors in ALL." (PMID 23773228, 2013). "For instance, IKAROS, encoded by IKZF1, has been shown to redirect BCR-ABL signaling from SFK activation to SLP65, which is downstream of the pre-B cell receptor tumor suppressor." (PMID 24130846, 2013). "During the last 5 years, IKZF1 has been established as one of the most clinically relevant tumor suppressors in ALL." (PMID 22528731, 2012). "Additionally, NX-2127 degrades CRBN neosubstrates Aiolos (IKZF3) and Ikaros (IKZF1), increasing T-cell activation and fostering anti-tumor effects." (PMID 41010009, 2025). "Indeed, molecular and pharmacological inhibition of CK2 restored IKZF1 function as a tumor suppressor." (PMID 39940843, 2025). "Similarly, IKZF1 (Ikaros) deletions or dominant-negative isoforms compromise its tumor-suppressive enhancer-silencing function, permitting SE-driven expression of cytokine receptors (CRLF2) and kinases (JAK2)." (PMID 41268574, 2025). "Since the N-terminal zinc finger domains are critical for IKZF1’s DNA-binding function, an alteration in these domains could arguably reduce IKZF1’s ability to bind to DNA and thus impair its role as a tumor suppressor by disrupted regulation of target genes." (PMID 37833543, 2023). "Whether IKZF1 as an enhancer of MM participates in the DSB repair pathway of tumor cells needs to be explored urgently." (PMID 35414773, 2022). "Whether and how IKZF1 as an enhancer of MM participates in the DNA repair pathway of tumor cells remains elusive." (PMID 35414773, 2022). "In this study, we assessed BCAT1 and IKZF1 methylation levels to quantify circulating tumor DNA (ctDNA) and investigated whether this method can be used to assess tumor burden and efficacy of therapy." (PMID 35000264, 2022). "IKZF1 encodes the protein IKAROS, an anti‐leukemic transcriptional factor that is highly conserved and essential for the differentiation of the B lineage in hematopoietic stem cells and as a tumor suppressor in B‐cell ALL." (PMID 33452870, 2021).